UCA1 (urothelial cancer associated 1)
Diseases named in the same sentence as UCA1 in open-access papers (continued):
Sharing a sentence is not in itself a finding about the gene and the disease.
prostate carcinoma (continued). "UCA1 enhances eIF4G1 levels via sponging miR-331-3p, while knockingdown of UCA1 sensitizes prostate cancer cells to radiotherapy by suppressing eIF4G1 expression via miR-331-3p/eIF4G1 axis." (PMID 33672592, 2021). "hsa-mir-204 has been widely studied in prostate cancer, which is negatively related to the expression of UCA1 and plays a role in tumor metastasis and sensitivity to chemotherapy." (PMID 34512870, 2021). "UCA1 inhibition rendered prostate cancer cells more sensitive to IR and resulted in accumulation of cells in the G2/M phase." (PMID 32585857, 2020). "In prostate cancer, lncRNA UCA1 enhances tumor cell radioresistance by inhibiting cell-cycle progression." (PMID 32934196, 2020). "UCA1 was abnormally up-regulated in tumor tissues from prostate cancer patients and patients with high UCA1 levels had a significantly poorer prognosis." (PMID 31760932, 2019). "The lncRNA, UCA1, is up-regulated in prostate cancer tissues and positively correlated with poor prognosis." (PMID 31178721, 2019). "As to prostate cancer, two top-ranked lncRNAs UCA1 and HOTAIR have been actually stored in the lnc2cancer database." (PMID 29108274, 2017). "In the present study, we intended to focus on a cancer-related lncRNA UCA1, which is overexpressed and functions as oncogenetic roles in various cancers, such as esophageal cancer, prostate cancer, renal cell carcinoma, and glioma." (PMID 29221199, 2017). "For instance, UCA1 has beens shwon to mediate radiosensitivity in prostate cancer cell lines and therefore might be a marker to predict response to radiotherapy in these patients." (PMID 37025585, 2023). "Our next study of UCA1 score combined with MRI is necessary for the diagnosis of prostate cancer." (PMID 35289508, 2022). "Long noncoding RNA (lncRNA) UCA1, which is expressed as a proto‐oncogene and plays a key role in tumorigenesis and tumor development, is highly expressed in various tumor tissues and cell lines, including prostate cancer." (PMID 35289508, 2022). "Compared with PCA3 and epiCaPture, UCA1 scores normalized to KLK2 may result in better performance in prostate cancer patients." (PMID 35289508, 2022). "The median UCA1 score for prostate cancer patients was 0.425 compared to −2.63 for benign patients." (PMID 35289508, 2022). "LncRNA UCA1 can regulate CXCR4 expression in prostate cancer cells to affect their progression." (PMID 35773731, 2022). "The UCA1 score of benign patients was significantly lower than that of nonhigh‐risk and high‐risk prostate cancer patients." (PMID 35289508, 2022). "In another study, however, UCA1 was confirmed may function as a ceRNA to reversely regulate ATF2 expression in prostate cancer, which is an interesting phenomenon worth further investigating." (PMID 36200182, 2022). "UCA1 has played a key role in studies of the effects of artesunate on prostate cancer." (PMID 35592755, 2022). "UCA1 score appears useful in detecting nonhigh‐risk (including very low‐, low‐, or intermediate‐risk) prostate cancer." (PMID 35289508, 2022). "In all patients (n = 897) we found that UCA1 score was superior to PSA only for detection of clinically insignificant, clinically significant, group 3 + 4 + 5 of WHO grade groups (Gleason score ≥4 + 3), and high‐risk prostate cancer with higher percentage." (PMID 35289508, 2022). "In the Fuzhou validation cohort, the UCA1 score also performed well in the detection of prostate cancer, nonhigh‐risk prostate cancer, D'Amico, and CAPRA." (PMID 35289508, 2022). "The UCA1 scores of benign patients were significantly lower than those of nonhigh‐risk prostate cancer patients (−2.63 vs. 0.16, p < 0.001; AUC 0.834)." (PMID 35289508, 2022). "In prostate cancer, lncRNA UCA1 levels were found to be positively correlated with eIF4G1 levels." (PMID 33672592, 2021). "lncRNA UCA1 promoted radioresistance in colorectal and prostate cancer." (PMID 32585857, 2020). "In Prostate cancer, UCA1 works as an oncogene by targeting miR-204." (PMID 31996265, 2020).
prostate carcinoma (continued). "Hence, ART exhibits anticancer properties through regulating the ceRNA crosstalk of the lncRNA UCA1/miR-184/BCL-2 axis in prostate cancer." (PMID 31178721, 2019). "Therefore, inhibition of UCA1 suppressed prostate cancer cells proliferation, migration and invasion." (PMID 29996942, 2018). "In addition, we provide evidence that UCA1 was up-regulated in prostate cancer tissues compared to hyperplastic prostatic tissues, and a higher UCA1 level predicted a poor prognosis in PCa patients." (PMID 28209917, 2017). "In addition, UCA1 was up-regulated in prostate cancer tissues compared to hyperplastic prostatic tissues, and a higher UCA1 level predicted poor prognosis in PCa patients." (PMID 28209917, 2017). "Notably, the UCA1 score of nonhigh‐risk prostate cancer patients was obviously higher than that of benign patients (median 0.160 vs. −2.630, p < 0.0001)." (PMID 35289508, 2022). "Furthermore, the UCA1 score performed well in distinguishing between nonhigh‐risk prostate cancer patients and benign patients, with an AUC value of 0.834." (PMID 35289508, 2022). "Thus, the mechanism underlying UCA1 effect on radioresistance involves cell cycle regulation in prostate cancer, but apparently not in CRC." (PMID 32585857, 2020). "Similarly, to discriminate CAPRA high‐risk from low‐ and intermediate‐risk prostate cancer patients, the AUC of the UCA1 score of 0.705 (95% CI, 0.609–0.800) was a bit better than that of serum PSA alone (AUC 0.671, 95% CI, 0.572–0.771) or the urine UCA1 test alone (AUC 0.672, 95% CI, 0.574–0.771)." (PMID 35289508, 2022). "UCA1 is an lncRNA similar to PCA3, and the mechanism of promoting the occurrence and development of prostate cancer has been widely explored." (PMID 35289508, 2022). "Specifically, ART regulates the lncRNA UCA1/miR-184/BCL-2 axis, to inhibit prostate cancer, while the has-circ-0043256/miR-1252/ITCH axis was involved in the treatment of non-small cell lung cancer by CA." (PMID 31178721, 2019). "Finaly, we analyzed patients without elevated PSA (<4) by ROC and found that UCA1 score had a significantly higher AUC than PSA only without missed diagnosis of prostate cancer." (PMID 35289508, 2022). "We analyzed patients without elevated PSA (<4) by ROC and found that UCA1 score had a significantly higher AUC (0.977) than PSA only (AUC 0.693) without missed diagnosis of prostate cancer." (PMID 35289508, 2022). "The number needed to test (NNT) to identify one prostate cancer patient at cutoff of −0.475 was approximately two individuals; if the UCA1 score was not used, four prostate biopsies were needed." (PMID 35289508, 2022). "Previous studies have reported that UCA1 and ATF2 showed a positive correlation in prostate cancer." (PMID 36200182, 2022). "Unlike in prostate cancer, UCA1 inhibition in CRC cells attenuated the G2/M arrest induced by IR, while it promoted apoptosis and inhibited migration and EMT of CRC cells." (PMID 32585857, 2020). "In summary, this is the first study to systematically interrogate the functional and clinical significance of UCA1 in prostate cancer, and we provide comprehensive evidence that it acts as a novel oncogenic lncRNA in PCa." (PMID 30940776, 2019).
glioma (37 papers, 2017 to 2024). A benign or malignant brain and spinal cord tumor that arises from glial cells (astrocytes, oligodendrocytes, ependymal cells). "LncRNA urothelial carcinoma-associated 1 (UCA1) has been found to stimulate the proliferation, migration, and invasion of cervical cancer cells or glioma cells by modulating the expression of miR-206, miR-122, and miR-182." (PMID 39170516, 2024). "Urothelial carcinoma-associated 1 (UCA1) lncRNA was recently discovered as a proto-oncogene in the progression of many cancers, including glioma in adults and pediatrics." (PMID 37444408, 2023). "Prognostic value: Higher expression of UCA1 was associated with higher glioma grade, poor prognosis, and survival." (PMID 34322395, 2021). "Another lncRNA, urothelial carcinoma-associated 1 (UCA1), was also reported to be induced in glioma cells by paracrine CXCL14 secretion from glioblastoma-associated stromal cells." (PMID 33050576, 2020). "More importantly, we found that higher expression of UCA1 in glioma tissues are associated with poor survival of glioma patients." (PMID 31596734, 2019). "This study investigated the functional role of UCA1 in glioma and explored the underlying molecular mechanisms." (PMID 31596734, 2019). "More importantly, the aberrant expression of UCA1 was associated with chemo-resistance to cisplatin and temozolomide in glioma cells via interacting with Wnt/β-catenin signaling." (PMID 31596734, 2019). "The long non-coding(lnc) RNA UCA1/micro RNA (miR)-182 axis has been regarded as a nodal driver of glioma invasion mediated by GB-associated stromal cells (GASCs) and GASC-secreted chemokine CXCL14." (PMID 31014014, 2019). "A recent study has indicated that lncRNA UCA1 modulates glioblastoma‐associated stromal cell‐mediated glycolysis and invasion of glioma cells." (PMID 30410864, 2018). "Therefore, therapeutic approaches designed to target the interactions and associations among the UCA1/miR-206/CLOCK attract our interest in treating glioma." (PMID 31798345, 2019). "UCA1 dysregulation was found to be associated with the chemosensitivity in glioma cells." (PMID 31596734, 2019). "Similarly, the long non-coding RNA UCA1/miR-182 has been observed to be a nodal driver of metastasis in glioma that is mediated by glioblastoma-associated stromal cells (GASCs) and the GASC-secreted chemokine CXCL14." (PMID 30234009, 2018). "UCA1, urothelial carcinoma-associated 1, is a lncRNA firstly cloned from the bladder cancer, which was latterly discovered as a proto-oncogene in the development of many human tumors like ovarian cancer, breast tumor, non-small cell lung cancer, and also glioma." (PMID 31798345, 2019). "Overexpressing Slug reversed the effects of UCA1 knockdown on glioma cell EMT and stemness, and their expression showed a positive association in glioma tissues." (PMID 39170516, 2024). "UCA1 is another lncRNA that induces glioma growth via EMT via TGF-β and functions as a competitive RNA for miR-1 and miR-203a." (PMID 37245177, 2023). "Identified as an oncogene, UCA1 expression was directly correlated to glioma grade and MGMT expression." (PMID 36105389, 2022). "Transfection of GBM cells, A172 and SHG44, with si-UCA1 showed decreased glioma cell viability with increased cell apoptosis." (PMID 36105389, 2022). "UCA1 knockdown inhibits proliferation and migration of glioma cells through miR-193a-mediated downregulation of cyclin-dependent kinase 6 (CDK6), and inactivates the PI3K/AKT pathway by decreasing the expression levels of phosphorylated PI3K and AKT proteins." (PMID 33777227, 2021). "UCA1 induces chemoresistance to cisplatin and temozolomide in glioma and decreases the sensitivity of BC cells to tamoxifen via the Wnt/β-catenin signaling pathway." (PMID 33777227, 2021).
glioma (continued). "In human glioma, UCA1 knockdown inhibits the proliferation and migration of cells through miR-193a-mediated downregulation of CDK6, and blocks the Notch signaling pathway by decreasing the expression levels of phosphorylated Notch1, Notch2 and Notch3 proteins." (PMID 33777227, 2021). "Upregulation of UCA1 is reported in glioma tissue and cell lines compared with the normal brain samples." (PMID 34322395, 2021). "This UCA1/miR-206/CLOCK axis was implicated to show the integrative effect on proliferation and cell cycle of glioma cells." (PMID 32344623, 2020). "Bioinformatic analysis and the experimental validation performed in glioma, a lethal malignant brain tumor, showed that lncRNA UCA1 regulate CLOCK genes via miR-206." (PMID 32344623, 2020). "UCA1 positively regulates PFKFB2 expression in glioma cells by functioning as a sponge against miR-182, which directly targets PFKFB2." (PMID 33050576, 2020). "Firstly, we aim to reveal the expression profiles of UCA1 in glioma tissues and cell lines by qRT-PCR experiments." (PMID 31798345, 2019). "In vivo comparisons and observations were also performed to investigate the role of UCA1 in glioma growth." (PMID 31798345, 2019). "In their results, UCA1 expression in glioma samples was higher than the contents in normal brain samples." (PMID 31798345, 2019). "Our qRT-PCR shows that UCA1 expression was remarkably elevated in glioma tissue and cell lines when comparing to normal tissues." (PMID 31798345, 2019). "Our results showed that UCA1 was up-regulated in glioma cells, and knock-down of UCA1 inhibited glioma cell growth, cell invasion and migration." (PMID 31596734, 2019). "Compared to normal tissues, UCA1 expressions were remarkably up-regulated in glioma tissues (p < 0.001)." (PMID 31798345, 2019). "Then we hope to know the role of UCA1 in the glioma cell migration and invasion by migration assay and invasion assay." (PMID 31798345, 2019). "On the other hand, overexpression of UCA1 promoted cell proliferation, cell invasion and migration in glioma cells." (PMID 31596734, 2019). "The levels of UCA1 in glioma tissues were divided into low and high expression based on the median expression level of UCA1." (PMID 31596734, 2019). "In the present study, we identified the up-regulation of UCA1 in glioma cell lines, and further functional study showed that UCA1 knock-down inhibited cell growth, cell invasion and migration, and also induced cell apoptosis." (PMID 31596734, 2019). "In conclusion, our results showed that UCA1 had a functional role in the regulation of glioma cell growth, invasion and migration, and chemo-resistance possibly via Wnt/β-catenin signaling pathway." (PMID 31596734, 2019). "Clinically, UCA1 was found to be up-regulated in glioma tissues and higher expression level of UCA1 was correlated with poor survival in patients with glioma." (PMID 31596734, 2019). "We examined the expression of UCA1 in glioma cell lines including SHG44, U251, U87 and SHG139 cells as well as human astrocytes by using qRT-PCR." (PMID 31596734, 2019). "The data confirmed that the growth of glioma tumors was suppressed by the silencing of UCA1 in vivo." (PMID 31798345, 2019). "Patients with high expression level of UCA1 in glioma tissues had significantly lower 5-year survival rate than those with low expression level of UCA1 (P<0.05, hazard ratio = 2.156, 95% confidence interval = 1.341-5.014, P<0.05)." (PMID 31596734, 2019). "Acting as a proto-oncogene, UCA1 was proved to promote the proliferation and cell cycle progression of glioma cells by upregulating cyclin D1 transcription." (PMID 31798345, 2019). "To our best knowledge, we are the first to propose that the axis of UCA1/miR-20/CLOCK plays a critical role in the regulation of glioma development." (PMID 31798345, 2019).
glioma (continued). "The results showed that glioma cells transfected with UCA1 siRNAs had significantly lower growth rate of glioma cells at 48 and 72 h post UCA1 siRNAs transfection than cells transfected with scrambled siRNA (P<0.05)." (PMID 31596734, 2019). "As UCA1 was up-regulated in the glioma cell lines, we chose the glioma cell lines, U87 and SHG139 that have the highest expression of UCA1 for the loss-of-function study." (PMID 31596734, 2019). "Overexpression of UCA1 promoted cell proliferation, cell invasion and migration in glioma cells, and promoted in vivo tumor growth of glioma cells." (PMID 31596734, 2019). "In 2018, Sun found that UCA1 enhanced the proliferation, migration, and invasion of glioma cells via the targeting of miR-122." (PMID 31798345, 2019). "The effects of UCA1 overexpression on glioma cell proliferation, cell invasion and migration were determined by CCK-8, cell invasion and wound healing assays, respectively." (PMID 31596734, 2019). "UCA1 was found to be highly up-regulated in glioma cells, and knock-down of UCA1 inhibited cell growth, invasion and migration, and also induced apoptosis in glioma cells." (PMID 31596734, 2019). "Consistently, our results showed that knock-down of UCA1 had inhibitory effects on glioma cell growth, cell invasion and migration, while overexpression of UCA1 promoted cell proliferation, cell invasion and migration in glioma cells." (PMID 31596734, 2019). "Overall, the UCA1/miR-182/PFKFB2 axis is associated with chemokine CXCL14 secretion, glycolysis, and invasion of glioma cells in GASCs." (PMID 31014014, 2019). "On the other hand, overexpression of UCA1 promoted cell proliferation, cell invasion and migration of glioma cells." (PMID 31596734, 2019). "In the clinical aspects, we found that UCA1 was up-regulated in glioma tissues and higher expression of UCA1 was positively correlated with the advanced tumor grade and predicted poor survival of glioma patients." (PMID 31596734, 2019). "Taken together, our results showed that UCA1 had a functional role in the regulation of glioma cell growth, invasion and migration, and chemo-resistance possibly via Wnt/β-catenin signaling pathway." (PMID 31596734, 2019). "Stable knockdown of lnc-UCA1 or overexpression of miR-627-5p in glioma cell lines (U87 and U251) were established to explore the function of lnc-UCA1 and miR-627-5p in glioma cells." (PMID 30518750, 2018). "The UCA1 level was further measured in glioma cells and cell spheres, and a qRT‐PCR result showed that it was remarkably upregulated in glioma cell spheres compared with the parental cells." (PMID 30410864, 2018). "Quantitative real-time PCR was conducted to profile the cell expression of lnc-UCA1 and microRNA-627-5p (miR-627-5p) in glioma tissues and cells." (PMID 30518750, 2018). "Cell Counting Kit-8 (CCK8) assay revealed that compared with NC group, a decrease occurred in proliferation ability of glioma cells in the UCA1(−) group (P < 0.05)." (PMID 30518750, 2018). "UCA1 knockdown inhibited the malignancies of glioma cells by reducing proliferation, migration, and invasion, but inducing apoptosis." (PMID 30518750, 2018). "Here, we report that the expression of UCA1 is significantly increased by transforming growth factor‐β (TGF‐β) treatment in glioma cells and is greater in glioma tissues than in normal adjacent tissues." (PMID 30410864, 2018). "Firstly, the UCA1 level was determined in glioma and normal tissues, and we found that it was remarkably upregulated in glioma tissues." (PMID 30410864, 2018). "qRT-PCR assay was conducted to assess UCA1 expression levels in normal brain tissues (NBTs), low-grade glioma tissues (grade I–II), high-grade glioma tissues (grade III–IV), as well as in NHAs and U87 and U251 glioma cells." (PMID 30518750, 2018).